ST13P4 (ST13, Hsp70 interacting protein pseudogene 4)
Synonyms: FAM10A4P; formerly FAM10A4
Gene: Transcribed processed pseudogene on chromosome 13 (50,172,089 to 50,173,181, forward strand). Ensembl gene ENSG00000232150.
Subcellular location: Cytoplasm
Diseases named in the same sentence as ST13P4 in open-access papers:
ST13P4 is named in the same sentence as 1 disease in open-access papers, as found by Europe PMC text mining. Sharing a sentence is not in itself a finding about the gene and the disease.
ST13P4 shares sentences with these, for which no sentence is quoted: cancer (1 paper).